FILIP1L (filamin A interacting protein 1 like)
Diseases named in the same sentence as FILIP1L in open-access papers (continued):
Sharing a sentence is not in itself a finding about the gene and the disease.
pancreatic cancer (2 papers, 2013 to 2021). "In order to test the expression levels of FILIP1L in various cancer cells, we measured FILIP1L mRNA expression in several human breast, colon, lung and pancreatic cancer cell lines by qRT-PCR." (PMID 24340050, 2013). "Our results demonstrate that cellular invasion is inversely correlated with FILIP1L expression in human breast, colon, lung and pancreatic cancer cells." (PMID 24340050, 2013). "In the present study, we have shown that FILIP1L expression is inversely correlated with the invasive potential of various cancer cell lines such as breast, colon, lung and pancreatic cancer." (PMID 24340050, 2013). "We tested whether FILIP1L expression is inversely correlated with the invasive potential of breast, colon, lung and pancreatic cancer cell lines." (PMID 24340050, 2013).
pulmonary adenoma (2 papers, 2022 to 2024). "Loss of FILIP1L increases xenograft growth, and, in lung-specific knockout mice, induces lung adenoma formation and mucin secretion." (PMID 36860703, 2022). "Our current experiments demonstrated that targeted knockout of FILIP1L leads to pulmonary adenoma formation in mice; these observations suggest that repression of FILIP1L is an important event during initiation or early progression of LUADs." (PMID 36860703, 2022).
adenoma (1 paper, 2022). A neoplasm arising from the epithelium. "Knocking out FILIP1L in mouse lungs led to TTF1-positive adenoma formation." (PMID 36860703, 2022). "Further studies are warranted to test whether these adenomas progress to adenocarcinomas if the Filip1l CKO mice were treated with cigarette smoke or other environmental carcinogens." (PMID 36860703, 2022).
cardiac hypertrophy (1 paper, 2020). "Additionally, these results are in line with previous reports that PRMT5 protected against cardiac hypertrophy by methylating GATA4 to hamper p300-mediacted GATA acetylation, and by symmetric di-methylating Histone H4R3 via regulation of Filip1L/β-catenin." (PMID 33424610, 2020).
colorectal adenocarcinoma (1 paper, 2023). The most common type of colorectal carcinoma. "For instance, the downregulation of FILIP1L causes the aberrant stabilization of a centrosome-associated chaperone protein, thereby driving aneuploidy and progression in colorectal adenocarcinoma." (PMID 37377953, 2023).
colorectal tumor (1 paper, 2016). "Here, we found that FILIP1L knockdown enhanced, while FILIP1L overexpression suppressed, human colorectal tumor cell migration and invasion." (PMID 27750216, 2016).
COVID-19 (1 paper, 2024). A disease caused by infection with severe acute respiratory syndrome coronavirus 2. "Human coronaviruses activate and hijack the proteostasis guardian HSF1 to enhance viral replication, and FILIP1L is downregulated in COVID-19." (PMID 38674024, 2024).
lymph node metastasis (1 paper, 2016). "Furthermore, higher FILIP1L levels were associated with reductions in tumor size, cell differentiation, lymphovascular invasion, cancer stage, depth of invasion, and lymph node metastasis (P = 0.019, < 0.001, 0.001, < 0.001, 0.005, and 0.002, respectively)." (PMID 27750216, 2016).
melanoma (1 paper, 2024). A malignant, usually aggressive tumor composed of atypical, neoplastic melanocytes. "FILIP1L is described to induce loss of proliferation and migration in endothelial cells and is known to inhibit melanoma growth when expressed in tumour-associated vasculature." (PMID 39030166, 2024).
mesenchymal tumors (1 paper, 2015). "FNDC3B, FILIP1L and P2RY5 (cluster II) were consistently up-regulated in mesenchymal tumors." (PMID 26295306, 2015).
mucinous adenoma (1 paper, 2022). "Thus, it will be worthwhile to evaluate whether FILIP1L knockout in a mutant Kras background will result in mucinous adenoma and/or adenocarcinoma formation in mouse lungs." (PMID 36860703, 2022).
mucinous colorectal adenocarcinoma (1 paper, 2022). "In mucinous colorectal adenocarcinoma (MAC), PFDN1 is a direct target of filamin A interacting protein 1-like (FILIP1L) and is degraded by the proteasome." (PMID 36438659, 2022).
serous cystadenocarcinoma (1 paper, 2016). A malignant serous cystic neoplasm usually involving the ovary or the pancreas. "In addition, administration of truncated mutant FILIP1L inhibited growth in human malignant melanoma tumor xenografts and serous cystadenocarcinoma cells by suppressing angiogenesis." (PMID 27750216, 2016).
triple-negative breast carcinoma (1 paper, 2025). An invasive breast carcinoma which is negative for expression of estrogen receptor (ER), progesterone receptor (PR), and human epidermal growth factor receptor 2 (HER2). "Similarly, upregulated FILIP1L inhibited metastasis of triple-negative breast cancer cells." (PMID 40303916, 2025).
tumor (20 papers, 2012 to 2025). "RUNX3 encodes a tumor suppressor which regulates cell growth, survival, differentiation, angiogenesis, and invasion; FILIP1L is a protein that inhibits metastases and chemoresistance; MT1E is a cytoskeleton-modifying protein, involved in cell migration and invasion." (PMID 36499753, 2022). "FILIP1L is known for its proven ability to inhibit the biological functions of a wide range of tumor cells and has the potential to be a therapeutic target for cancer." (PMID 40303916, 2025). "For instance, Filip1l, which undergoes an early-to-mid-life transition, acts as a tumor suppressor in mucinous colon cancer." (PMID 38594255, 2024). "Collectively, these findings suggest that FILIP1L downregulation leads to neoplastic changes associated with adenocarcinoma differentiation, confirming the tumor suppressor function of FILIP1L in the lungs." (PMID 36860703, 2022). "Knockdown of FILIP1L significantly enhanced growth of subcutaneous tumor xenografts in athymic nude mice." (PMID 36860703, 2022). "Knockdown of FILIP1L significantly enhanced tumor growth compared with controls in both Filip1l-knockdown cell lines." (PMID 36860703, 2022). "Importantly, from the RNA-sequencing analysis of these tumors, reduction of FILIP1L is associated with upregulated Wnt/β-catenin signaling, which has been implicated in proliferation of cancer cells as well as inflammation and fibrosis within the tumor microenvironment." (PMID 36860703, 2022). "A key differentially methylated region was located in a potential enhancer of the tumour suppressor gene Filip1l and its expression was reduced in mouse tumours." (PMID 34000624, 2021). "As tumour suppressor gene inactivation is an important feature of cSCC, differential methylation at regions of potential regulatory relevance is likely an important process of tumour suppressor silencing in cSCC as indicated by the Filip1l locus." (PMID 34000624, 2021). "In order to determine expression of the Filip1l protein in mouse cSCC tumours and control skin, immunoblotting was used." (PMID 34000624, 2021). "For both keratinocyte and stem-cell like tumour samples, we found the Filip1l and Cmss1 genes to be differentially methylated in both, human and mouse cSCC." (PMID 34000624, 2021). "Deregulation of DNA methylation is an important feature of murine and human cSCC that likely contributes to silencing of tumour suppressor genes, as shown for Filip1l." (PMID 34000624, 2021). "Filip1l is downregulated in many types of tumor cells, and its overexpression results in inhibition of cell proliferation and increased apoptosis." (PMID 30275866, 2018). "FILIP1LΔC103 (COOH terminal truncation mutant 1-790 of Filamin A Interacting Protein 1-Like) has been identified to hold therapeutic potential for suppressing tumor growth." (PMID 29100323, 2017). "We then showed that FILIP1L expression in endothelial cells led to decreased cell migration and increased apoptosis, and that tumor vessel-expression of FILIP1L blocked in vivo tumor growth." (PMID 27776341, 2016). "We also demonstrated FILIP1L has an anti-angiogenic function that over-expression of FILIP1L in endothelial cells led to decreased cell migration and increased apoptosis, and that tumor vessel-expression of FILIP1L blocked in vivo tumor growth." (PMID 27776341, 2016). "siRNA-mediated FILIP1L knockdown enhanced tumor cell migration and invasion and inhibited apoptosis and cell cycle arrest in COLO205 cells." (PMID 27750216, 2016). "Our results indicate that doxorubicin induction of FILIP1L leads to cell death and that this potential mechanism of resistance should be further explored in tumor cells." (PMID 22900064, 2012). "Importantly, the function of FILIP1L’s decrease in enhancing tumor invasion and metastasis is mainly achieved by promoting the Wnt/β-catenin signaling pathway." (PMID 39682415, 2024). "FILIP1L is a tumor suppressor with diminished expression in various tumors." (PMID 37377953, 2023).
tumor (continued). "This study identifies FILIP1L as a tumor suppressor in LUADs and demonstrates that downregulation of FILIP1L is a clinically relevant event in the pathogenesis and clinical course of these neoplasms." (PMID 36860703, 2022). "Next, we examined whether FILIP1L expression and FILIP1L promoter methylation were related to tumor progression." (PMID 36860703, 2022). "Collectively, these results strongly suggest that downregulation of FILIP1L is clinically relevant in LUAD and warrant further efforts to evaluate pharmacologic regimens that either directly or indirectly restore FILIP1L-mediated gene regulation for the treatment of these neoplasms." (PMID 36860703, 2022). "In addition, Filip1l-knockdown tumors show considerable central necrosis that is an evidence of higher proliferation rate outpacing tumor blood supply [as shown in the stitched images of the tumors]." (PMID 36860703, 2022). "The DMR covering intronic regions of Cmss1 and Filip1l is hypermethylated in tumours." (PMID 34000624, 2021). "Furthermore, in murine cSCC tumours, the Filip1l protein levels were further reduced compared to VS (paired t-test, p = 0.0026)." (PMID 34000624, 2021). "Together these results support the observation that FILIP1L may be a useful tumor marker whose expression is inversely correlated with poor prognosis, stage and chemoresistance, possibly due to its role in inhibiting WNT/β-catenin pathway." (PMID 27776341, 2016). "We showed that loss of FILIP1L expression increases with tumor progression, resulting in a significant difference between primary and metastatic ovarian cancer samples, whereas the levels of β-catenin and SLUG increase with tumor progression." (PMID 27776341, 2016). "Negative FILIP1L expression was independently associated with poor overall survival after adjustment for several covariates, such as age, sex, tumor size, lymphovascular invasion, perineural invasion, and cancer stage (HR: 1.62; 95% CI: 1.07–2.46; P = 0.023)." (PMID 27750216, 2016). "In addition, targeted expression of FILIP1L in the tumor vasculature inhibited tumor growth in vivo." (PMID 24340050, 2013). "Overall, these findings suggest that FILIP1L may be an important inhibitor of cancer cell invasion and metastasis in a wide variety of tumor types." (PMID 24340050, 2013). "We initially identified FILIP1L in the setting of tumor angiogenesis." (PMID 24340050, 2013). "Furthermore, since FILIP1L expression is lost in a variety of human tumor types, a correlation between reduced expression levels of FILIP1L and impaired response to doxorubicin chemotherapy should be explored." (PMID 22900064, 2012). "Overall, these results suggest that FILIP1L is downregulated (at least in part) by promoter methylation, which is associated with heavy smoking in patients with LUAD, and that FILIP1L downregulation is associated with a more aggressive (less differentiated) tumor histology." (PMID 36860703, 2022). "Whereas FILIP1L downregulation also correlated with FILIP1L promoter methylation in LUSC specimens, neither appeared to be associated with cigarette smoking, suggesting that factors other than cigarettes contribute to epigenetic repression of this tumor suppressor gene in these neoplasms." (PMID 36860703, 2022). "Additionally, genes that are critical to cancer growth and metastasis, such as AURKB, PCNA, fascin, and FILIP1L, may also play a role in the cooperative anti-tumor activity of vitamin C and buparlisib." (PMID 33664847, 2021). "The dynamic regulation of FILIP1L and TOM1L1 along the developmental trajectory of tumor cells from sensitivity to resistance provides insights into the molecular complexity of therapy resistance." (PMID 40303916, 2025). "LUZP1 shows homology to FILIP1 (Filamin A Interacting Protein 1), a protein interactor of filamin and actin, and FILIP1L (FILIP1 Like), a suppressor of tumor cell migration." (PMID 33869174, 2021).
tumor (continued). "Following the literature, a tumor-promoting activity for the up-regulation of MCOLN2 and the down-regulation of FILIP1L and BCL2L10 can be hypothesized." (PMID 32911675, 2020). "In addition, Filamin A interacting protein 1-like (FILIP1L), which was reported to be down-regulated in EOC and negatively correlated with EOC tumor stages, chemoresistance, and patient survival, has been found to induce β-catenin degradation." (PMID 31829231, 2019). "Up-regulated expression of FILIP1L could lead to induction of tumor cell apoptosis and tumor cell proliferation inhibition, FILIP1LΔC103 (COOH terminal truncation mutant 1-790 of FILIP1L) is more effective than wild-type FILIP1L in mediating these activities." (PMID 29100323, 2017). "Overall, these findings suggest that down-regulation of FILIP1L is clinically relevant in LUAD, and warrant further efforts to evaluate pharmacologic regimens that either directly or indirectly restore FILIP1L-mediated gene regulation for the treatment of these neoplasms." (PMID 36860703, 2022).
cancer (10 papers, 2012 to 2025). A tumor composed of atypical neoplastic, often pleomorphic cells that invade other tissues. "We also demonstrate that FILIP1L promoter methylation is associated with FILIP1L down-regulation in these cancer cells." (PMID 24340050, 2013). "Overall, these findings suggest that down-regulation of FILIP1L associated with DNA methylation is related with the invasive phenotype in various cancers." (PMID 24340050, 2013). "In summary, we have demonstrated that down-regulation of FILIP1L is associated with the invasive phenotype in cancer cells of various histologies." (PMID 24340050, 2013). "Collectively, these data suggest that down-regulation of FILIP1L is associated with an invasive phenotype in various cancer cell lines and that this phenotype can be reversed by overexpression of FILIP1L." (PMID 24340050, 2013). "FILIP1L promoter methylation is associated with down-regulation of FILIP1L in these cancer cells." (PMID 24340050, 2013). "Filamin A interacting protein 1-like (FILIP1L) is a multifunctional protein that plays a role in cancer progression, apoptosis, and angiogenesis." (PMID 40206462, 2025). "Our previous studies have suggested that FILIP1L is downregulated by promoter methylation in various cancer histologies." (PMID 36860703, 2022). "We previously showed that FILIP1L is downregulated by promoter methylation in cancer cell lines of various histologies including lung, ovarian, colon, breast, and pancreas." (PMID 36860703, 2022). "Collectively, these observations suggest that epigenetic repression of FILIP1L enhances the malignant phenotype of cancer cells via Wnt/β-catenin signaling." (PMID 36860703, 2022). "In summary, we have shown that a tumor suppressor FILIP1L is downregulated in the majority of human cancer types." (PMID 36860703, 2022). "We originally observed that FILIP1L was down-regulated through promoter methylation, and its down-regulation induced an invasive phenotype in various types of cancer cells including ovarian." (PMID 27776341, 2016). "A previous study showed that FILIP1L inhibited cancer cell invasion and metastasis by blocking WNT/β-catenin signaling pathway activity." (PMID 27750216, 2016). "Correspondingly, knockdown of FILIP1L in FILIP1L-high expressing, low-invasive cancer cell lines resulted in increase of cell invasion." (PMID 24340050, 2013). "We observed that overexpression of FILIP1L inhibited the invasive potential of aggressive cancer cell lines of these histologies." (PMID 24340050, 2013). "Further, FILIP1L expression was inversely correlated with the invasive potential of these cancer cells." (PMID 24340050, 2013). "MRNA expression of FILIP1L was highest in normal primary cells and cell line compared to cancer cell lines." (PMID 24340050, 2013). "To definitively prove that FILIP1L inversely regulates invasive properties of the cancer cells, we tested if knockdown of FILIP1L in FILIP1L-high expressing, low-invasive cancer cell lines resulted in an increase in cell invasion." (PMID 24340050, 2013). "Increased expression of FILIP1L resulted in inhibition of migration in endothelial cells and inhibition of migration and invasion in cancer cells." (PMID 24340050, 2013). "Re-expression of FILIP1L in FILIP1L-low expressing, highly-invasive cancer cell lines resulted in inhibition of cell invasion." (PMID 24340050, 2013). "We then tested if overexpression of FILIP1L in FILIP1L-low-expressing, highly-invasive cancer cell lines resulted in inhibition of cell invasion." (PMID 24340050, 2013). "In order to test if the protein expression of FILIP1L is correlated with its mRNA expression in these various cancer cells, we measured FILIP1L protein expression by immunoblot analysis using anti-FILIP1L antibody." (PMID 24340050, 2013). "Treatment of these cells with DNA demethylating agent 5-aza-2’-deoxycytidine (DAC) resulted in significantly increased FILIP1L mRNA expression in all four cancer histologies." (PMID 24340050, 2013).